FAP (fibroblast activation protein alpha)
Diseases named in the same sentence as FAP in open-access papers (continued):
Sharing a sentence is not in itself a finding about the gene and the disease.
cancer (continued). "In conclusion, the first studies on FAP-specific PET in cancer patients show promising results, especially when considering the advances in the field of radiation oncology in general." (PMID 32942573, 2020). "FAP is a glycoprotein that is expressed in fibrotic tissues and various cancer cells but is rarely expressed in normal human and mouse tissues." (PMID 32858947, 2020). "The relationship between FAP expression and poor clinical outcome of cancer patients is quite well known." (PMID 33207686, 2020). "In the 19 included studies, FAP was evaluated in various cancers and showed promising initial results for staging as well as radiotherapy planning." (PMID 32942573, 2020). "Due to high-level, cell surface expression of FAP in cancer-promoting CAFs, FAP has been considered a prime therapeutic target in the cancer stroma with potential for clinical application." (PMID 33308315, 2020). "The MEDLINE database was searched for the use of FAP-specific PET in cancer patients and the records were screened according to PRISMA guidelines." (PMID 32942573, 2020). "Fibroblast activation protein alpha (FAPα): FAPα is expressed in the CAFs of ~90% of all carcinomas." (PMID 32194856, 2020). "Taking into account the recent successes of radioligand therapy in neuroendocrine and prostate cancer, targeting FAP also presents a promising new approach in the treatment of these FAP-positive tumors." (PMID 30072500, 2019). "It is therefore likely that the successful application of FAP-targeted by BiTE-armed oncolytic adenovirus in cancer patients will require the development of an optimized therapeutic approach." (PMID 30683154, 2019). "This study establishes ICO15K-FBiTE as an effective strategy for targeting both cancer cells and FAP-positive stromal cells, killing through combined viral oncolysis and intratumoral expression of an anti-FAP BiTE." (PMID 30683154, 2019). "Of these compounds, FAPI-04 has been recently introduced as a theranostic radiotracer and demonstrated high uptake into different FAP-positive tumors in cancer patients." (PMID 30850501, 2019). "It was shown that the expression of FAP prolyl endopeptidase, even on the cell surface or solubilized in the plasma, correlates with the malignancy and cisplatin resistance of carcinomas." (PMID 31881770, 2019). "The presented efficacy studies support the role of the FAP-targeted immunocytokine FAP-IL2v as a versatile combination partner for cancer immunotherapy and serve to inform the selection of combination partners for clinical studies." (PMID 30400822, 2018). "FAP expression was observed in both GCAFs (61.1%) and cancer cells (86.3%), mainly in the cytoplasm." (PMID 30038550, 2018). "In a transgenic mouse model, targeted depletion of FAP-expressing CAFs resulted in increased cancer cell death." (PMID 30103384, 2018). "Another key player between CAFs and cancer cells is the fibroblast activation protein (FAP), which mediates cancer cell invasion and cell cycle activation by Rb protein inhibition." (PMID 30428588, 2018). "As with any other targeted approach, FAPI-02 achieves optimal results only in tissues with a sufficiently high FAP expression, which is known to be rather heterogeneous in different cancer types and patients." (PMID 29626120, 2018). "The anti-FAP antibody sibrotuzumab has been labeled with 131I and used for therapy in patients with metastasized FAP-expressing carcinomas." (PMID 29626120, 2018). "As a genetically stable molecule expressed on the cell surface and selectively upregulated on reactive stromal fibroblasts in a broad range of cancers, FAP is an attractive target for antitumour therapy." (PMID 28158223, 2017). "Better understanding of the biology of FAP and FAP-expressing cells is needed to improve the design of FAP targeting regimens for cancer treatment." (PMID 28158223, 2017).
cancer (continued). "Our data suggest that USP7 inhibitors can be used for treatment of CID-deleted APC mutated CRCs, as well as for potential preventive therapy for FAP patients carrying germline APC mutations, by delaying cancer onset." (PMID 29045831, 2017). "Then, sibrotuzumab, an antibody directed against humanized F19, was produced and used in a Phase I dose-escalation study, which showed the safety of this antibody in patients who suffer from advanced or metastatic FAP α-positive cancers." (PMID 26985769, 2016). "Our data show that vaccination against FAP significantly improves the therapeutic efficacy of the traditional cancer vaccine by destroying FAP+ stroma cells." (PMID 26943036, 2016). "This is further supported by other genes that correlated closely in many cancer forms such as FAP, PDGFRB, THBS2 and VCAN which are also markers for matrix-producing cells and in some cases also for cancer-associated fibroblasts." (PMID 27809802, 2016). "The expression of FAP in CAFs is reported in various carcinomas and is used as an important marker of CAF." (PMID 27881889, 2016). "Strategies have been developed to utilize the presence FAP-expressing stromal cells in the treatment of cancer." (PMID 26252379, 2015). "Eca109 cancer cell nests were surrounded by activated mice fibroblast cells, which were fibroblast activation protein-α (FAPα)-positive by immunohistochemistry." (PMID 26511079, 2015). "Ubiquitous expression by the majority of the stroma of epithelial tumors makes FAPα an ideal target for cancer therapy." (PMID 25593080, 2015). "The cancer-specific distribution and function of FAP make this protein eligible as a novel prognostic marker and therapeutic target in tumors." (PMID 25775399, 2015). "The expression of FAP was found predominantly in stromal cells and slightly in cancer cells in resected PDAC tissues." (PMID 26330349, 2015). "Previous studies have demonstrated that FAP-α has an important role in development of cancers by modifying bioactive of substrate peptides and their cellular functions." (PMID 24885257, 2014). "Recent studies have provided convincing evidence that targeting FAP-α is a promising method in both diagnosis and treatment of cancer." (PMID 24885257, 2014). "Fibroblast activation protein (FAP) was suggested to be a potential target antigen since FAP is widely expressed by various epithelial and mesenchymal cancer types." (PMID 23937772, 2013). "In previous studies, FAP-expressing fibroblasts were reported to enhance the cancer cell invasion by producing ECM, and have essential functions in maintaining muscle mass and hematopoiesis." (PMID 24354864, 2013). "The observed enhanced directionality and velocity of cancer cells invading through FAP+ 3D matrices was effectively reversed in matrices produced from FAP+ fibroblasts in the presence of FAP enzymatic inhibitor." (PMID 21668992, 2011). "Some reports suggest that FAP expression can occur in both the stroma and epithelial compartments of cancers." (PMID 21668992, 2011). "Among miR-204 gene targets that are potential regulators of cell-matrix interaction and proteolysis, overexpression of APRC1B, CTSC, FAP, MMPs, BMP1, CDH11 and ITGB4 is associated with cancer metastasis and/or poor prognosis." (PMID 20369013, 2010). "Such behavior suggested its suitability for stromal targeting and/or cancer detection and therapy, and in recent years has underpinned the development of a humanized anti-FAP antibody (sibrotuzumab) and the implementation of clinical trials." (PMID 18447899, 2008). "The concept of anti-FAP antibody-based cancer immunotargeting has even been proven in a clinical Phase I dose-escalation study." (PMID 17105646, 2006). "FAP is a type II membrane-bound protease capable of remodeling the extracellular matrix by degrading collagen and modifying bioactive signaling peptides in cancer." (PMID 41594225, 2026).
cancer (continued). "In Cohort 3 (HKI2), stromal FAP expression was higher in metastatic versus non‐metastatic cancers (Mann–Whitney U test, p = 0.01), but epithelial FAP and stromal αSMA were not statistically different between metastatic and non‐metastatic cancers (p = 0.05 and p = 0.19, respectively)." (PMID 41410015, 2026). "Moreover, FAP-targeting cyclic peptide radiopharmaceuticals are more advantageous and have greater potential for cancer therapy." (PMID 39747850, 2025). "We have observed the promising potential of FAP‐targeted PET/CT in cancer diagnosis, which may serve as a viable alternative to FDG PET/CT for certain cancers." (PMID 40656546, 2025). "Moreover, K2+ EVs activated fibroblasts into a cancer-associated phenotype, increasing α-SMA and FAP expression." (PMID 40643553, 2025). "However, cancer patients demonstrated significantly lower median FAP concentrations before radiation therapy as compared to healthy volunteers." (PMID 40690098, 2025). "Consequently, several studies have reported on the use and efficacy of [177Lu]Lu-FAP-2286 in various cancers, with case reports further supporting these findings." (PMID 40766056, 2025). "Furthermore, fibroblasts exposed to CC cells typically undergo conversion to cancer-associated fibroblasts (CAFs), as evidenced by increased CAF markers (e.g., ACTA2, FAP, COL1A2, VIM)." (PMID 40055606, 2025). "FAP has a low expression in or is absent from healthy adult tissues, but is highly expressed in cancer-associated fibroblasts and pericytes in the majority of human epithelial cancers." (PMID 39852848, 2025). "FAP are proteins that highly expressed in CAFs across multiple cancers." (PMID 40248695, 2025). "Thus, FAP has been considered as a pan-cancer target inseveral preclinical approaches and clinical trials." (PMID 39954291, 2025). "Therefore, FAP-targeting CAR-T cell therapy is expected to show higher efficacy when combined with other cancer immunotherapies." (PMID 40707476, 2025). "The specific expression pattern of FAP implies that it is a potential therapeutic target for diseases, and FAPI variants labeled with therapeutic radionuclides, such as 177Lu and 225Ac, have recently been assessed in different cancers." (PMID 40384987, 2025). "Thus, further molecular and functional analysis of FAP+ cCAFs is imperative to understand the role of these cells in prostate and other cancer types, and in metastasis." (PMID 38634185, 2025). "FAP expression has been reported in various types of cancers, including gynecologic malignancies." (PMID 40867237, 2025). "Additional compounds targeting FAP are in various stages of development, and a FAP agent may become the standard of care for cancer imaging." (PMID 40863874, 2025). "Thus, a co-culture containing both CAFs and cancer cells is more representative and forms a more reliable model compared to FAP-overexpressing cancer cell lines that are now often used." (PMID 40016527, 2025). "However, further investigations are still necessary to clarify the role and properties of FAP+ fibroblasts across different kinds of cancers." (PMID 40438108, 2025). "PET/CT scans of 21/21 patients with different malignancies including breast, pancreatic, and thyroid cancer demonstrated uptake of [68Ga]Ga-FAP-2286 within primary solid tumours, adjacent excised tissues, and metastatic lesions, suggesting the potential of a general cancer tracer." (PMID 41049848, 2025). "It is unlikely that FAP PET will play a significant role in staging of these cancers." (PMID 39572227, 2025). "In a different strategy, inhibiting the CXCR4-CXCL12 pathway (which is activated by FAP+ CAFs) could be effective in treating cancers." (PMID 40707476, 2025). "Fibroblast activation protein (FAP) is transmembrane serine protease that has attracted increasing attention due to its expression being almost exclusive to pathological conditions, including fibrosis, arthritis, and cancer." (PMID 41373408, 2025).
cancer (continued). "FAP positive CAFs are thought to be instrumental in the development of immunosuppressive TME and high expression of FAP has been associated with poorer prognosis in various cancers." (PMID 40741380, 2025). "Moreover, FAP inhibitors developed as positron emission tomography / computed tomography (PET/CT) scan are anticipated to be a powerful imaging tool to detect cancer and fibrosis in situ." (PMID 40293537, 2025). "From these clusters, five major cell types were identified via classical cell markers, including T cells (CD3E, CD8A, CD3D), B cells (CD19, MS4A1, CD79A), myeloid cells (CD14, CD68, LYZ), endothelial cells (PECAM1, VWF, CDH5) and cancer-associated fibroblasts (CAFs) (ACTA2, FAP, PDGFRB)." (PMID 39941131, 2025). "Notably, TGN reduced the transformation of fibroblasts into cancer-associated fibroblasts (CAFs) through the downregulation of α-SMA and FAP (Fibroblast activation protein) expression, indicating its capacity to normalize the TME." (PMID 40027190, 2025). "Cancer-associated fibroblasts demonstrate FAP expression, unlike the normal fibroblasts from which they differentiate." (PMID 40867237, 2025). "FAP inhibitors (FAPI) can be combined with ß-emitters such as [18F] or [68Ga] to be used in PET for diagnostic purposes and staging across different types of cancers." (PMID 40022163, 2025). "FAP positive CAFs present both challenges and opportunities for targeted cancer therapies." (PMID 40741380, 2025). "For example, a co-culture containing both CAFs and cancer cells could be used in preclinical studies evaluating the potential of FAP-targeting radiotracers." (PMID 40016527, 2025). "The remodulation of the TME by FAP+ fibroblasts through reshaping the extracellular matrix have already been reported, and the overexpression of FAP+ fibroblasts indicates poor prognosis in various cancers." (PMID 40438108, 2025). "Although much about FAP biology remains unknown, several novel therapeutic approaches to combat cancer and other disease states by targeting FAP have been described in the literature." (PMID 40542914, 2025). "Fibroblast activation protein (FAP), a type II transmembrane serine protease belonging to the dipeptidyl peptidase 4 family with both dipeptidyl peptidase and endopeptidase activity, is overexpressed on CAFs in more than 90% of epithelial carcinomas." (PMID 40006089, 2025). "Thus, successful development of FAP-targeted anti-cancer interventions can be beneficial for a large number of solid cancers." (PMID 39073475, 2024). "REVs were found to enhance the expression of CAFs related proteins like αSMA, CD95, EMT marker vimentin, SLC1A5, and STAT3 phosphorylation as well as FAP expression after 48 hours exposure to REVs and SEVs suggesting that REVs can subvert stromal fibroblasts to adopt a cancer-promoting phenotype." (PMID 39431017, 2024). "Furthermore, encouraging results from preclinical and clinical studies justify further clinical evaluation of [68Ga]Ga-FAP-2286 in cancer diagnostics and the availability of a simple synthesis procedure." (PMID 39338305, 2024). "However, it is important to note that FAP can also be expressed in cancer cells in GBM, as reported by us and others." (PMID 38705944, 2024). "Furthermore, we analyzed the relationship between FAP expression and immune infiltration in all types of cancer." (PMID 39055892, 2024). "Our findings emphasize that the circNOX4/FAP/IL-6 axis could be exploited as a therapeutic target for CAF-based cancer therapy." (PMID 38459511, 2024). "Cancer cells were also FAP-positive in four out of six cases of primary adenocarcinoma." (PMID 39188902, 2024). "Moreover, FAP’s enzymatic activities extend beyond its role in cancer, as it is also involved in various pathological conditions such as fibrosis and arthritis." (PMID 39335703, 2024). "Fibroblast activation protein (FAP) is another potential CAF marker in various cancers." (PMID 39403603, 2024).
cancer (continued). "Fibroblast activation protein (FAP) is a serine protease characterized by its high expression in cancer-associated fibroblasts (CAFs) and near absence in adult normal tissues and benign lesions." (PMID 38543239, 2024). "Anti-FAP NIR-PIT could be considered as an adjunctive therapy with other cancer drugs, such as cytotoxic treatment or immune checkpoint inhibitors." (PMID 38275890, 2024). "Similarly, our findings revealed increased FAP protein expression during cancer progression, suggesting its involvement in these protumoral processes." (PMID 38606999, 2024). "Our work again highlighted the close relatedness of rhesus and human CRCs as emphasized by upregulation of MMPs, telomerase, WNT pathway key proteins, or FAP and downregulation of cancer suppressive mechanisms such as cytotoxic T cells and other immune cell populations and Wnt inhibitory proteins." (PMID 38504345, 2024). "The FAP staining intensity reflects the degree of cancer fibrosis." (PMID 38951801, 2024). "As expected, the FAP IHC study revealed that healthy lung sections were FAP-negative, and that cancer-associated fibroblasts from lung tumors were strongly positive." (PMID 39188902, 2024). "Furthermore, PET/CT imaging using [68 Ga]-radiolabeled inhibitors of FAP utilizes CAFs to detect cancer tissue, thus enabling the classification of disease extent and spread based on CAF abundance." (PMID 38328551, 2024). "Fibroblast activation protein (FAP) is an attractive target for cancer theranostics." (PMID 39718718, 2024). "ATMSC which uptook either nEV (nEV-ATMSC) or MpEV (MpEV-ATMSC) showed no significant changes in the expression of cancer-associated fibroblast markers (e.g., FAP, FSP, Vimentin)." (PMID 38515582, 2024). "Additionally, the pro-tumorigenic functional role of FAP to remodel the cancer tissue promoting cell proliferation, migration and invasion can be targeted as part of therapeutic intervention." (PMID 39579201, 2024). "FAP is a type II transmembrane serine protease, almost exclusively expressed in pathological conditions such as fibrosis, arthritis, and cancer, which was first identified in cultured fibroblasts by Wolfgang Rettig in 1986 and described as a cell surface antigen." (PMID 39055892, 2024). "Thus, the amount of damage inflicted to the cancer cell heavily depends on the FAP-expression level by the CAFs, the spatial location of the CAFs, and the penetration depth of the selected radionuclide." (PMID 39718718, 2024). "Thus, the combination of FAP-targeted and cancer cell-targeted NIR-PIT has the potential to enhance each other’s therapeutic effects." (PMID 38555315, 2024). "In order to reduce the rate of clearance of the tracer in the blood, we also added Phe to increase the lipid solubility of the ligand, and finally designed and synthesized a double-specific dimer radiotracer targeting SSTR2 and FAP for cancer imaging and even future therapeutic studies." (PMID 39770488, 2024). "Using scRNA-seq data, we investigated the expression of genes involved in stromal-like signature (FAP, VIM, and ITGB1); cancer-associated fibroblasts (CAFs; POSTN and ACTA2); as well as COL1A1, SULF1, TCF21, and DLK1, which were previously associated with FAP-high or FAP-low CAF phenotypes in OC." (PMID 39634630, 2024). "This suggests that FAP might play a divergent role in the pathophysiology of certain cancers, offering potential avenues for developing targeted treatments." (PMID 38558814, 2024). "The presence of fibroblasts in the 3D cancer models provides the possibility of testing cancer drugs directed against the fibroblasts themselves, e.g. PDGFR-β and FAP-α that were both expressed in the 1BR.3.G fibroblast, are potential therapeutic targets in cancer." (PMID 39011470, 2024). "Fibroblast activation protein α (FAPα) is recognized as a highly useful molecular target, and its inhibitor, FAPI, is a compound capable of theranostics, both therapeutic and diagnostic, for cancer treatment." (PMID 39596363, 2024).